USP46 (ubiquitin specific peptidase 46)
Description:
Deubiquitinating enzyme that plays a role in behavior, possibly by regulating GABA action. May act by mediating the deubiquitination of GAD1/GAD67 (By similarity). Has almost no deubiquitinating activity by itself and requires the interaction with WDR48 to have a high activity. Not involved in deubiquitination of monoubiquitinated FANCD2.
Synonyms: FLJ12552
Tractability: PROTAC: ubiquitination databases record sites on it; its protein half-life has been measured.
Target class: Enzyme; Hydrolase
Gene: Protein-coding gene on chromosome 4 (52,590,960 to 52,659,301, reverse strand). Ensembl gene ENSG00000109189.
Subcellular location: Cytoplasm
Subcellular location (Human Protein Atlas): Nucleoli; Nucleoli rim
Gene Ontology:
Molecular function: cysteine-type deubiquitinase activity; protein binding; deubiquitinase activity
Biological process: positive regulation of canonical Wnt signaling pathway; protein deubiquitination; regulation of synaptic transmission, GABAergic; regulation of postsynaptic neurotransmitter receptor internalization
Cellular component: cytoplasm; peptidase complex; glutamatergic synapse; synapse
Genetic constraint (gnomAD): Loss-of-function variants: 10 observed, 35.17 expected, observed/expected ratio (o/e) 0.28, 90% interval 0.17 to 0.48. The upper end of that interval is the gene's LOEUF score, 0.48, which puts it in group 2 of 6, group 1 being the genes least tolerant of losing a copy. Missense variants: 231 observed, 411.57 expected, observed/expected ratio (o/e) 0.56, 90% interval 0.5 to 0.63. Synonymous variants: 145 observed, 152.74 expected, observed/expected ratio (o/e) 0.95, 90% interval 0.83 to 1.09.
Homologues: Orthologues: mouse Usp46 (100% identical), pig USP46 (100% identical), guinea pig USP46 (99% identical), rat Usp46 (99% identical), chimpanzee USP46 (97% identical), macaque USP46 (97% identical), dog USP46 (97% identical), rabbit USP46 (97% identical), zebrafish usp46 (94% identical), Drosophila melanogaster Usp12-46 (72% identical), Caenorhabditis elegans usp-46 (69% identical). Paralogues in human: USP12 (89% identical), USP39 (24% identical).
Diseases named in the same sentence as USP46 in open-access papers:
USP46 is named in the same sentence as 36 diseases in open-access papers, as found by Europe PMC text mining. Sharing a sentence is not in itself a finding about the gene and the disease. The quoted sentences say what the papers report.
colon cancer (7 papers, 2013 to 2026). "For example, a study on colon cancer indicates USP46 is a tumor suppressor whereas in human papilloma virus transformed cancers, USP46 is necessary for the proliferation of the tumor cells." (PMID 34845193, 2021). "Further, an enhanced degradation of the PHLPP Ser/Thr protein phosphatase tumor suppressor appeared to be the result of reduced USP46 mRNA expression under hypoxic conditions in colon cancer cells." (PMID 31208103, 2019). "As a functional consequence of the hypoxia-reduced USP46 levels, the colon cancer cell lines SW480 and HCT116 showed increased chemotherapy resistance." (PMID 31208103, 2019). "Similarly, in colon cancer cells hypoxia reduces USP46 mRNA and protein levels and, therefore, diminishes USP46’s stabilizing effect on the tumor suppressors PHLPP1 and PHLPP2, conferring to the colon cancer cells an increased paclitaxel resistance." (PMID 27014628, 2016). "Downregulation of USP46 may serve as a biomarker of resistance to chemotherapy in colon cancer." (PMID 27014628, 2016). "USP32, USP1, USP37, USP12, and USP6 are elevated in macrophages, while USP32, USP9X, USP46, USP12, USP36, and USP24 are upregulated in classical monocytes of colon cancer relative to the control group." (PMID 41356798, 2026). "Similarly, USP46‐mediated PHLPP1 and PHLPP2 stabilization decreases cell proliferation and tumorigenesis in colon cancer cells." (PMID 41000374, 2025). "A different study revealed that USP46 functions as a tumor suppressor by binding to PHLPP and directly removes the polyubiquitin chains from PHLPP, resulting in inhibited Akt signaling in colon cancer." (PMID 23472206, 2013).
cervical carcinoma (4 papers, 2015 to 2025). A carcinoma arising from either the exocervical squamous epithelium or the endocervical glandular epithelium. "HPV E6 has also been shown to regulate the function of another USP; E6 forms a complex with USP46 in cervical cancers cells." (PMID 40011575, 2025). "Concurrently, E6 forms a complex with the deubiquitinating enzyme USP46 in cervical cancer cells, promoting interaction between USP46 and Cdt2 (a component of the CRL4Cdt2 E3 ubiquitin ligase complex)." (PMID 41488306, 2025). "We found that the viral E6 and human USP46 complex increases the levels of Cdt2 in cervical cancers." (PMID 35008200, 2021).
depression (4 papers, 2013 to 2021). "SNP analyses in a Japanese population confirmed USP46 as a gene linked to major depressive disorder in humans." (PMID 27310475, 2016). "In animal experiments, USP46 has been shown to be responsible for the induction symptoms of depression, as measured by the tail mobility in a CS mouse strain." (PMID 27310475, 2016). "In this test, Usp46 MT and KO mice displayed a lower sucrose preference, indicating that these mice seem to be behaviorally in a depression-like state." (PMID 23472206, 2013). "Importantly, USP46 knock-out (KO) mice exhibit similar changes in depression-like behaviors and broad expression of a wild type USP46 transgene in CS mice rescued these behaviors." (PMID 29302259, 2017). "Although USP46 single nucleotide polymorphism (SNP) has been reported to be associated with major depressive disorder and with depressive temperament in human, no study has been conducted to examine the association of the USP46 gene with PTSD in a clinical sample." (PMID 34456759, 2021).
bipolar disorder (3 papers, 2011 to 2017). A disorder of the brain that causes unusual shifts in mood, energy, activity levels and the ability to carry out day-to-day tasks. "Thus, the Usp46-deficient mouse cannot be characterized as a model mouse for depressive or manic disorders with the present data." (PMID 23472206, 2013).
breast carcinoma (3 papers, 2011 to 2024). "The first biomarker is gene USP46, which is a broadly expressed gene reported as one gene associated with breast cancer and glioblastomas." (PMID 21342590, 2011). "Interestingly, however, increased levels of USP12 and USP46 have been associated with the progressions of several cancers, including breast cancer, liver cancer, and multiple myeloma." (PMID 39506038, 2024). "To validate the results of our screens, we used Crispr/Cas9 technology to knockout (KO) the USP12, USP46, WDR20, and WDR48 genes either individually or in combination in at least two different mouse fibroblast and human breast cancer MDA-MB-231 cell clones, respectively." (PMID 39506038, 2024).
colorectal cancer (3 papers, 2020 to 2023). A primary or metastatic malignant neoplasm that affects the colon or rectum. "We also found a decrease in LRP6 levels upon knockdown of USP46 in the colorectal cancer cell line, DLD1." (PMID 37798301, 2023). "USP46 has equally shown a tumor suppressor activity in renal cell carcinoma with a similar mechanism to that described in colorectal cancer." (PMID 33029497, 2020). "In colorectal cancer, USP46 has been shown to increase the stability of PHPLL1; hence, we investigated the protein levels of USP46 and PHPLL1 in lung cancer tissues." (PMID 33029497, 2020). "In this study, we showed that USP46 expression is downregulated in patients with lung cancer, suggesting a tumor suppressor role of USP46 in lung cancer, which is consistent with the reports from other studies in colorectal cancer and renal cell carcinoma." (PMID 33029497, 2020). "Previously, in colorectal cancer, USP46 had been shown to antagonize the activity of AKT by deubiquitinating PHLPP1." (PMID 33029497, 2020). "Consistent with the antiproliferation activity of USP46, the protein was found to be downregulated in colorectal cancer, suggesting that USP46 is an important tumor suppressor gene." (PMID 33029497, 2020). "In colorectal cancer, USP46 has been shown to promote the stabilization of PHLPP1 and subsequent inhibition of the AKT pathway." (PMID 33029497, 2020). "USP46 had been shown to deubiquitinate the PH domain leucine-rich repeat protein phosphatase 1 (PHLPP1) in colorectal cancer." (PMID 33029497, 2020). "Moreover, studies have shown that USP7, USP10, USP33, and USP46 are all involved in the progression of colorectal cancer." (PMID 37371055, 2023). "Wnt-driven cancers that could be targeted by USP46 inhibitors include invasive breast cancer, glioblastomas, and colorectal cancer (CRC)." (PMID 37798301, 2023).
glioblastoma (2 papers, 2011 to 2023). The most malignant astrocytic tumor (WHO grade IV). "We asked if there is a difference in Wnt target gene expression in glioblastoma tumors stratified by expression of the components of the USP46 complex." (PMID 37798301, 2023). "Alterations in USP46 mostly consisted of amplification and were commonly observed in glioblastoma multiforme and lung squamous cell carcinomas." (PMID 37798301, 2023).
glioma (2 papers, 2017 to 2023). A benign or malignant brain and spinal cord tumor that arises from glial cells (astrocytes, oligodendrocytes, ependymal cells). "However, the expression and prognosis of KIT, CHIC2, EXOC1, IGFBP7, RASL11B or USP46 in glioma are unclear." (PMID 36043552, 2023).
lung carcinoma (2 papers, 2020 to 2023). "This study is aimed at investigating the role of USP46 in lung cancer tumorigenesis and identifying its underlying mechanisms." (PMID 33029497, 2020). "At the same time, we elucidated related proteins that directly act on PHLPPs in lung cancer, including USP46 through the effect of PHLPP1 on AKT, and the effect of miR-205 on PHLPP2 and miR-190 on PHLPP1." (PMID 37576883, 2023). "Collectively, these results established the role of USP46 in inhibiting cell proliferation in lung cancer cells by promoting the stability of USP46 and subsequently inhibiting the AKT pathway." (PMID 33029497, 2020). "We also showed that USP46 antagonizes the activity of the AKT pathway that affects the proliferation of lung cancer cells." (PMID 33029497, 2020). "Subsequently, we sought to identify potential mechanisms through which USP46 regulates cell proliferation in lung cancer cells." (PMID 33029497, 2020). "The protein level of USP46 was further evaluated in the lung cancer tissues of 8 patients, and as expected, the lower level of USP46 mRNA in the cancer tissue compared to the adjacent normal tissue correlated with the protein level." (PMID 33029497, 2020). "Subsequently, we evaluated the role of USP46 in the cell proliferation of several lung cancer cell lines." (PMID 33029497, 2020). "Using qRT-PCR, the expression of USP46 was measured in lung cancer tissues and adjacent normal tissues in 30 patients." (PMID 33029497, 2020). "We examined the ability of USP46 to regulate cell proliferation in lung cancer cells via cell proliferation assay, radiation assay, genetic overexpression and knockdown, and chemical inhibition of relevant genes." (PMID 33029497, 2020). "USP46 is downregulated in lung cancer and suppresses the proliferation of lung cancer cells by inhibiting the PHLPP1/AKT pathway." (PMID 33029497, 2020). "Collectively, these results indicate the role of USP46 in inhibiting lung cancer cell proliferation during DNA damage." (PMID 33029497, 2020). "Our study has identified USP46 as an important negative regulator of cell proliferation in lung cancer cells." (PMID 33029497, 2020). "USP46 was further shown to inhibit lung cancer cell proliferation under conditions of normal growth and during radiation-induced DNA damage by antagonizing the ubiquitination of PHLPP1 resulting in the inhibition of AKT signaling." (PMID 33029497, 2020). "Exposure to radiation and AKT inhibition significantly reversed the effect of USP46 siRNA on lung cancer cell proliferation." (PMID 33029497, 2020). "We also compared the expression of USP46 in several human lung cancer cell lines to normal human bronchial epithelial (HBE) cells and found that USP46 expression was greatly decreased both in mRNA levels and protein levels in the lung cancer cell lines compared to HBE cells." (PMID 33029497, 2020). "We also established an adverse clinical correlation of USP46 expression in lung cancer patients." (PMID 33029497, 2020). "USP46 is a deubiquitinase, so we hypothesized that USP46 deubiquitinates PHLPP1 in lung cancer cells." (PMID 33029497, 2020). "Therefore, present results suggested that USP46 might be positively correlated with PHLPP1 in lung cancer tissues." (PMID 33029497, 2020). "Compared to the control cells, the overexpression of USP46 led to a decrease in ubiquitination in PHLPP1, indicating that USP46 deubiquitinates PHLPP1 in lung cancer cell lines." (PMID 33029497, 2020). "Quantitative real-time polymerase chain reaction (qRT-PCR) and western blotting (WB) were used to measure the expression levels of USP46 and PHLPP1 in lung cancer tissue and adjacent normal tissue from patients with lung cancer." (PMID 33029497, 2020). "Herein, we investigated the potential role of USP46 in lung cancer tumorigenesis and found that the expressions of USP46 and PHLPP1 were downregulated in lung cancer." (PMID 33029497, 2020).
lung carcinoma (continued). "In effect, both USP46 and PHPLL1 were downregulated in lung cancer tissues compared to the adjacent cancer tissues." (PMID 33029497, 2020). "Conversely, we showed that the downregulation of USP46 increases the proliferation of lung cancer cells, and exposure to radiation in combination with an AKT inhibitor suppresses the proliferation of the lung cancer cells." (PMID 33029497, 2020). "In this study, we identified a strong downregulation of the expressions of USP46 and PHLPP1 in lung cancer tissues relative to normal adjacent tissues." (PMID 33029497, 2020). "On this basis, the expression of both USP46 and PHLPP1 were found in low level in lung cancer." (PMID 37576883, 2023). "However, the detailed relationship between USP46 and the PHLPP1/AKT pathway is still less investigated in lung cancer." (PMID 33029497, 2020). "Clinically, we showed that USP46 and PHLPP1 are downregulated in patients with lung cancer." (PMID 33029497, 2020).
mental disorder (2 papers, 2011 to 2013). A disease that has its basis in the disruption of mental process. "Taken together, these results suggest that Usp46 controls a broad range of behavioral phenotypes, and presently, it is difficult to extrapolate the behavioral phenotype of Usp46-deficient mice to any specific mental disorders." (PMID 23472206, 2013). "This work indicates that behavioral despair associated mutant of the Lys 92 deletion of USP46 could influence enzyme activity and therefore might contribute to the understanding of the molecular mechanisms of the mental disorders associated with USP46." (PMID 22043315, 2011). "Elucidating the function of Usp46 at both the cellular and central nervous system level may provide further insight into the regulating mechanisms of behavioral phenotypes of Usp46-deficient mice which can extrapolate to human mental disorders." (PMID 23472206, 2013). "The Lys 92 deletion of USP46 could influence enzyme activity and might contribute to the understanding of the neural and genetic mechanisms that underlie the mental disorders associated with this gene, thereby provide a molecular clue how the enzyme regulating the pathogenesis of mental illnesses." (PMID 22043315, 2011). "In order to assess the broader functional significance of Usp46 for behavioral phenotypes that might be related to mental disorders in humans, we subjected Usp46 MT and KO mice to a variety of behavioral tests." (PMID 23472206, 2013). "However, our finding, that the Lys 92 deletion of USP46 influences enzyme activity, provides a molecular clue in the interpretation how the enzyme regulates the pathogenesis of mental illnesses." (PMID 22043315, 2011).
myocardial infarction (2 papers, 2021 to 2025). Gross necrosis of the myocardium, as a result of interruption of the blood supply to the area, as in coronary thrombosis. "In addition, USP46 overexpression promoted myocardial infarction, and we found that USP46 restored myocardial infarction inhibited by miR-33a-5p mimics, indicating that miR-33a-5p protects against myocardial I/R injury through down-regulation of USP46." (PMID 34845193, 2021). "Circ-NNT or USP46 knockdown or miR-33a-5p overexpression inhibited the expression of pro-caspase-1, cleaved caspase-1, pro-caspase-11, cleaved caspase-11, IL-1β, and IL-18 in A/R cardiomyocytes and attenuated myocardial infarction in I/R mice." (PMID 34845193, 2021).
anal carcinoma (1 paper, 2024). "In addition, the proliferation and differentiation of HPV‐positive anal cancer cells require the involvement of the histone deubiquitination enzyme USP46, which makes USP46 a target for the treatment of this type of cancer." (PMID 39184862, 2024).
cervical tumors (1 paper, 2021). "In this paper we compared real cervical tumors with matched normal tissue from same patients and found that the effects of E6 mediated USP46 activation are indeed reflected as increased levels of Cdt2 and decreased levels of Set8 protein in the real tumors." (PMID 35008200, 2021).
HCMV infection (1 paper, 2023). "We did not directly test the role of the UAF1 scaffold in HCMV infection, as its knockdown is likely to have pleiotropic effects due to the combined loss of USP1, USP12, and USP46 activity." (PMID 37289831, 2023).
infarction (1 paper, 2021). A localised pathological necrosis of tissue resulting from obstruction of the blood supply usually by a thrombus, an embolus, or vascular torsion. "Our subsequent studies demonstrated that circ-NNT and USP46 positively regulate and miR-33a-5p negatively regulates A/R-induced cardiomyocytes pyroptosis in vitro and I/R-induced myocardial pyroptosis and infarction in vivo." (PMID 34845193, 2021).
invasive breast carcinoma (1 paper, 2023). A carcinoma that infiltrates the breast parenchyma. "High levels of USP46 correlated with reduced survival of patients with cancers such as invasive breast cancer." (PMID 37798301, 2023).
leukemia (1 paper, 2013). A malignant (clonal) hematologic disorder, involving hematopoietic stem cells and characterized by the presence of primitive or atypical myeloid or lymphoid cells in the bone marrow and the blood. "More information concerning the cellular function of the normal USP46 is clearly needed in order to understand the role of RUNX1-USP42 fusions in leukemias." (PMID 23877199, 2013).
melanoma (1 paper, 2025). A malignant, usually aggressive tumor composed of atypical, neoplastic melanocytes. "DANCR is a melanoma-associated lncRNA and conserved small non-coding RNA host gene that is expressed from equivalent regions in diverse vertebrate genomes and in a similar direction relative to the neighbouring USP46 and RASL11B protein coding genes." (PMID 41336739, 2025).
Myocardial fibrosis (1 paper, 2021). "USP46 knockdown relieved myocardial fibrosis and myocardial cell degeneration and decreased gap widening with the increasing treatment time." (PMID 34845193, 2021).
post-traumatic stress disorder (1 paper, 2021). An anxiety disorder precipitated by an experience of intense fear or horror while exposed to a traumatic (especially life-threatening) event. "We investigated whether genetic variants in the ubiquitin carboxyl-terminal hydrolase 46 (USP46) would be associated with post-traumatic stress disorder (PTSD) in people with exposure to combat trauma using a case-control candidate gene association design." (PMID 34456759, 2021).